CNTN4 (contactin 4)
Description:
Contactins mediate cell surface interactions during nervous system development. Has some neurite outgrowth-promoting activity. May be involved in synaptogenesis.
Synonyms: BIG-2; AXCAM
Tractability: Antibody: its Gene Ontology location is reachable by antibodies, with high confidence; UniProt places it where antibodies can reach, with medium confidence; UniProt predicts a signal peptide or a membrane-spanning region. PROTAC: its protein half-life has been measured.
Gene: Protein-coding gene on chromosome 3 (2,098,813 to 3,057,963, forward strand). Ensembl gene ENSG00000144619.
Subcellular location: Cell membrane; Secreted
Pathways (Reactome):
Metabolism of proteins: Post-translational modification: synthesis of GPI-anchored proteins
Gene Ontology:
Molecular function: cell-cell adhesion mediator activity
Biological process: negative regulation of neuron differentiation; nervous system development; axon guidance; axonal fasciculation; axonogenesis; brain development; dendrite self-avoidance; homophilic cell-cell adhesion; neuron cell-cell adhesion; neuron projection development; regulation of synaptic plasticity; synapse organization
Cellular component: axon; extracellular region; plasma membrane; synapse
Genetic constraint (gnomAD): Loss-of-function variants: 66 observed, 111.45 expected, observed/expected ratio (o/e) 0.59, 90% interval 0.49 to 0.73. The upper end of that interval is the gene's LOEUF score, 0.73, which puts it in group 2 of 6, group 1 being the genes least tolerant of losing a copy. Missense variants: 1,225 observed, 1,288.2 expected, observed/expected ratio (o/e) 0.95, 90% interval 0.91 to 1. Synonymous variants: 503 observed, 461.94 expected, observed/expected ratio (o/e) 1.09, 90% interval 1.01 to 1.17.
Gene-disease validity (ClinGen):
ClinGen rates the evidence that CNTN4 causes each of these diseases.
complex neurodevelopmental disorder (autosomal dominant): Disputed. A disorder that involves more than one phenotype associated with the central nervous system, including but not limited to intellectual disability, autism, and seizures (epilepsy).
Homologues: Orthologues: chimpanzee CNTN4 (98% identical), dog CNTN4 (97% identical), macaque CNTN4 (96% identical), pig CNTN4 (96% identical), mouse Cntn4 (95% identical), guinea pig CNTN4 (95% identical), rat Cntn4 (94% identical), rabbit CNTN4 (91% identical), tropical clawed frog cntn4 (75% identical), zebrafish cntn3b (57% identical). Paralogues in human: CNTN3 (64% identical), CNTN6 (60% identical), CNTN5 (55% identical), CNTN2 (44% identical), CNTN1 (43% identical), NRCAM (29% identical), L1CAM (29% identical), CHL1 (28% identical), NFASC (27% identical), NEO1 (24% identical), ROBO1 (24% identical), ROBO2 (23% identical), and 24 more.
Diseases named in the same sentence as CNTN4 in open-access papers:
CNTN4 is named in the same sentence as 54 diseases in open-access papers, as found by Europe PMC text mining. Sharing a sentence is not in itself a finding about the gene and the disease. The quoted sentences say what the papers report.
schizophrenia (19 papers, 2011 to 2025). A major psychotic disorder characterized by abnormalities in the perception or expression of reality. "By integrating the results from different prediction approaches, they identified six top candidates that represent promising causal genes for schizophrenia (CNTN4, GATAD2A, GPM6A, MMP16, PSMA4, and TCF4), including the GPM6A gene." (PMID 35328011, 2022). "Disruption of Cntn4 is known to cause developmental delay and mental retardation, as well as autism, while Ntng1 mutations are a cause of Rett syndrome and have been implicated in the pathophysiology of schizophrenia." (PMID 23251410, 2012). "We transformed these proteins to their encoding gene IDs and identified the top 20 genes as the most probable schizophrenia-risk genes, including the EYA3, CNTN4, HSPA8, LRRK2, and AFP genes." (PMID 37966892, 2023). "Dysregulation of the genes FURIN, TSNARE1, CNTN4, CLCN3 and SNAP91 have been implicated by eQTL analysis of schizophrenia GWAS hits, which were later separately prioritized by chromatin interaction analysis of schizophrenia risk variants." (PMID 35972862, 2022). "Among the 41 prioritized causal genes, CNTN4, GATAD2A, GPM6A, MMP16, PSMA4, and TCF4 represent the most promising causal genes for schizophrenia." (PMID 29540662, 2018). "In contrast, PSMA4 was significantly downregulated and CNTN4 showed a trend of downregulation (P = 0.065) in the hippocampus of schizophrenia cases compared with controls." (PMID 29540662, 2018). "In the prefrontal cortex, CNTN4 was significantly downregulated in schizophrenia cases in both GSE53987 (P < 0.01) and GSE21138 (P < 0.01) datasets." (PMID 29540662, 2018). "The specific phenotypes observed in Cntn4-deficient mice may be used to study the mechanisms underlying increased responsiveness or vigilance, a trait observed across many different human disorders such as attention-deficit hyperactivity disorder, post-traumatic stress disorder, and schizophrenia." (PMID 26958094, 2016). "TOP2B2 peaks from untreated cells are associated with three genes (CNTN4, IMMP2L and SATB2) implicated in both autism and schizophrenia whilst TOP2B2 peaks from E2-treated cells are associated with five genes (CNTN4, IMMP2L, EPC, SMG6 and CACNA1C)." (PMID 26459242, 2015). "Three loci, including DPP10 on chromosome 2q14.1 and two genes in close proximity on chromosome 3p26.3, CNTN4 and CHL1, both encoding cell adhesion molecules, confer very strong susceptibility to autism, schizophrenia, and related disease." (PMID 23185133, 2012). "As schizophrenia is believed to have its origins in neural development, CNTN4 may be an important candidate gene for schizophrenia." (PMID 37966892, 2023). "Interestingly, the participant with schizophrenia and personality disorder also had a duplication in the CNTN4 gene." (PMID 29693535, 2018). "Of note, five (CNTN4, GATAD2A, GPM6A, MMP16, and TCF4) of the top six causal genes are involved in neurodevelopment, further supporting the neurodevelopmental hypothesis of schizophrenia." (PMID 29540662, 2018). "Additionally, a nonsynonymous SNP of this gene was associated with the effects of olanzapine and risperidone on negative symptoms of schizophrenia, indicating that CNTN4 may serve as a risk signal for the identification of schizophrenia." (PMID 37966892, 2023). "Indeed, common single-nucleotide variants in the CNTN4 locus have recently been associated with other neuropsychiatric disorders, such as schizophrenia, perhaps pointing to a non-disorder specific contribution of this cell adhesion gene in neuropsychiatric pathogenesis." (PMID 26958094, 2016). "The duplications not currently classified as pathogenic or a VUS in the schizophrenia-LIQ individuals overlapped several interesting neuropsychiatric candidate genes, such as CNTN4, NDUFV2, and RCAN1." (PMID 29187259, 2017).
autism (18 papers, 2011 to 2025). Persistent deficits in social interaction and communication and interaction as well as a markedly restricted repertoire of activity and interest as well as repetitive patterns of behavior. "CNTN4 is one of the genes lost in 3p deletion syndrome, of which autism is a common clinical feature, and disruption of CNTN4 alone causes neurodevelopmental delay and an autistic phenotype." (PMID 35445171, 2017). "Three cases carrying a copy number variant (CNV) in the CNTN4 gene were reported by the Autism Genome Project Consortium (AGP)." (PMID 26958094, 2016). "Rare copy number variations (CNVs) in CNTN4 have been reported to influence autism susceptibility in Asian populations." (PMID 24756565, 2014). "CNTN4 (contactin 4) is a neural cell adhesion molecule whose gene has been reported to be associated with autism and developmental delay in multiple studies." (PMID 23922650, 2013). "The autistic behavior of patient 41 may be becauseof CNTN4 (contactin 4), previously introduced as astrong candidate gene associated with autism spectrumdisorders." (PMID 31210441, 2019). "Moreover, its paralogs CNTN2 and CNTN4 are associated with epilepsy and autism, respectively." (PMID 30148849, 2018). "The phenotype is variable, with autism more likely in individuals with larger duplications that include CNTN4." (PMID 40760574, 2025). "Deletions and duplications of the CNTN4 gene, which plays an important role in neuronal maintenance and plasticity, have also been described in autism patients." (PMID 37107578, 2023). "Deletions and duplications in the CNTN4 gene or its promoter region were found in 10 families of the Autism Genetic Resource Exchange (AGRE) collection." (PMID 26958094, 2016). "However, considering the role of purine metabolic disorders in autism, role for CNTN4 and ITPR1 in the regulation of SUA seems plausible and needs to be evaluated further." (PMID 27039371, 2016). "Disruption of Cntn4 in the C57BL/6J background does not affect specific autism-related phenotypes in developing or adult mice but causes subtle non-disorder specific changes in sensory behavioral responses and cognitive performance." (PMID 26958094, 2016). "First, a deletion at the 5′ end of the CNTN4 gene has been identified in an autism patient." (PMID 24756565, 2014). "The CNTN4 deletions we uncovered are similarly highly enriched in the ADHD and autism cases and corroborate previous reports." (PMID 37120522, 2023). "Currently, CNTN4, CNTN5, and CNTN6 are suggested as potential disease genes for autism." (PMID 24756565, 2014). "In the Autism Case-Control cohort (ACC), deletion in the promoter region of CNTN4 was found in three cases but not in controls." (PMID 26958094, 2016).
autism spectrum disorder (11 papers, 2008 to 2025). A spectrum of developmental disorders that includes autism, and Asperger syndrome. "The neuronal cell adhesion molecule contactin-4 (CNTN4) is genetically associated with autism spectrum disorder (ASD) and other psychiatric disorders." (PMID 38745463, 2024). "Variants that disrupt CNTN4 have been associated with autism spectrum disorder (ASD) as well as milder phenotypes, including speech delay, cognitive impairment and neurobehavioral phenotypes." (PMID 37628571, 2023). "Studies have found that NRXN–NLGN links synaptic function to cognitive disease, and the mutations in the NRXN-1 and CNTN4 genes have been reported to cause autism spectrum disorders (ASD)." (PMID 36142685, 2022). "Other important genes identified by gene-based GWASs include neural adhesion molecules CNTN4 (p = 3.88e-9) on chr3p26.3-p26.2 which has been linked to autism spectrum disorders, PCSK5(p = 2.88e-11) on chr9q21.13, and CDH13 (p = 4.19e-8) on chr16q23.3) and TMEM132 (p = 2.18e-8) on chr17q12." (PMID 34868193, 2021). "Copy number changes of close family members CNTN4, CNTN5, and CNTN6 have been associated with autism spectrum disorders." (PMID 28126037, 2017). "Duplications in CNTN4 have been observed in cohorts of individuals with autism spectrum disorder." (PMID 40894639, 2025). "Additionally, 3p26.3 contains the dosage-sensitive gene CNTN4 (OMIM 607280), recently recognized as a risk factor for autism spectrum disorder and other neuropsychiatric disorders of unknown etiology." (PMID 36553064, 2022).
Cognitive impairment (6 papers, 2015 to 2025). Abnormal cognition is characterized by deficits in thinking, reasoning, or remembering. "Disruption of CNTN4 is also thought to cause cognitive defects." (PMID 27039371, 2016). "The 3p deletion involved four pathogenic genes (CHL1, CNTN6, CNTN4, ITPR1) associated with cognitive impairment, ataxia, and motor dysfunction." (PMID 41384039, 2025). "Alterations in CNTN4 expression have been implicated to negatively affect the proteolytic processing of APP, which contributes to impairments in axon guidance and synaptic plasticity, reduced neuronal survival, and ultimately results in cognitive impairments." (PMID 33519384, 2020). "Similar to other CNVs involving synaptic and neurodevelopmental genes, the CNVs disrupting the CNTN6/CNTN4 region have also been reported in patients with intellectual disabilities, cognitive disorders, severe anorexia nervosa, and bipolar disorder in addition to ASD." (PMID 26257835, 2015). "The present study shows, however, that despite these hippocampal deficits, Cntn4 does not contribute to general cognitive impairment." (PMID 33542194, 2021).
Intellectual disability (5 papers, 2011 to 2022). "Pertinently, studies have found that CNTN4 is associated with mental retardation and affects intelligence." (PMID 35907915, 2022). "A prime example of implementation of such a strategy is with contactin 4 (CNTN4), and its association with social and intellectual disability in a recurrent deletion syndrome." (PMID 25161627, 2014). "In addition the CHL1 gene, mapping at 3p26.3 distally to CRBN and CNTN4, was proposed as candidate gene for a non specific mental retardation because of its high level of expression in the brain." (PMID 21457564, 2011).
developmental delay (4 papers, 2012 to 2017). "Both duplications disrupted the gene encoding Contactin, CNTN4, which has been implicated in developmental delays and ASDs." (PMID 28281572, 2017). "Genetic haploinsufficiency of contactin-4 was demonstrated to cause developmental delay." (PMID 24659297, 2014).
microcephaly (4 papers, 2014 to 2025). A congenital or acquired developmental disorder in which the circumference of the head is smaller than normal for the person's age and sex. "Deletions of both CNTN4 and CNTN6 genes have been reported in the 3p deletion syndrome, which is characterized by low birth weight, growth restriction, DD, ID, hypotonia, and microcephaly." (PMID 26257835, 2015).
bipolar disorder (3 papers, 2011 to 2015). A disorder of the brain that causes unusual shifts in mood, energy, activity levels and the ability to carry out day-to-day tasks. "Bipolar disorder with alcohol dependence and other co-morbidities was associated with SNP rs2727943 (p = 3.3×10−8) on chromosome 3p26.3 located between the genes contactin-4 precursor (BIG-2) and contactin 6 (CNTN6)." (PMID 22205951, 2011).
neuroblastoma (3 papers, 2010 to 2024). Neuroblastoma (NB) is the most common solid, extracranial childhood tumor. "This is the first GWAS study to investigate an association with germline telomere length in neuroblastoma patients, and we found that the CNTN4 gene is associated with changes in germline telomere length in Korean neuroblastoma patients." (PMID 35902621, 2022). "The neuroblastoma cell line SH-SY5Y is a well-established model for the differentiation of cells into cortical-like neurons and was used to evaluate the single and double loss-of-function of CNTN4 and APP on neuronal differentiation in vitro." (PMID 38745463, 2024). "Although the details remain unclear, the effect of CNTN4 on the development of nerve endings and the development of neuroblastoma should be examined in future functional studies." (PMID 35902621, 2022). "CNTN4−/−, APP−/− and CNTN4−/−/APP−/− SH-SY5Y neuroblastoma cell lines were generated by CRISPR-Cas9 gene editing." (PMID 38745463, 2024).
Alzheimer disease (2 papers, 2011 to 2022). A progressive, neurodegenerative disease characterized by loss of function and death of nerve cells in several areas of the brain leading to loss of cognitive function such as memory and language. "Although Cntn4 was significantly enriched only in 14-day KA GCs after MF sprouting has developed, we also shortlisted this gene, because it has been linked to circuit formation, target specification, synaptic plasticity, neurodevelopmental disorders, and Alzheimer’s disease." (PMID 36117624, 2022).
Anxiety (2 papers, 2016 to 2021). Intense feelings of nervousness, tension, or panic often arise in response to interpersonal stresses. "The observed hyperresponsivity in Cntn4-deficient mice was unrelated to anxiety levels, as mice showed similar exploratory behaviors in classical anxiety behavioral tests, such as the elevated plus maze and open field." (PMID 26958094, 2016). "Thus, CNTN4 genetic mutations may affect hippocampal functionality at the neuro-anatomical, electrophysiological, and behavioral level which is of relevance to the display of maladaptive anxiety responses that are observed in several neuropsychiatric disorders." (PMID 33542194, 2021). "Although speculative, the increased startle response together with the enhanced acquisition in the Barnes maze could indicate that Cntn4 deficiency in the C57BL/6J background leads to a state of increased behavioral responsiveness without overt anxiety or avoidance behavior in mice." (PMID 26958094, 2016).
breast carcinoma (2 papers, 2015 to 2022). "3p would include TGFBR2, CNTN4, and CHL1 (reported for colorectal cancer) and CNTN6 (for breast cancer), as well as FHIT, ROBO1-GRE1 and SETMAR-LRRN1." (PMID 26247464, 2015).
diabetes (2 papers, 2011 to 2015). "Therefore, our findings and existing published evidences can lead to the hypothesis that mutations in the CNTN4 gene modify its binding with TCF3 in the pancreas and VSX1 in the brain and activate related genetic regulations for diabetes and its complications." (PMID 25898945, 2015).
major depressive disorder (2 papers, 2018 to 2022). An episode of depression lasting two or more weeks without an intervening episode of mania. "Two other patients (Case 5 with CNTN4 deletion and Case 6 with MACROD2 deletion) had a comorbidity of major depressive disorder." (PMID 35611833, 2022).
malaria (2 papers, 2021 to 2025). Malaria is a serious and sometimes fatal disease caused by a parasite that commonly infects a certain type of mosquito which feeds on humans. "Genes with top scores encode for different malaria relevant functions such as regulation of inflammation (CSMD1), neural adhesion (CNTN4, PCSK5, CDH13, TMEM132), vascular epithelial development (FLT4), and protein kinases (PTPRT, PRKG1)." (PMID 34868193, 2021).
Obesity (2 papers, 2010 to 2015). Accumulation of substantial excess body fat. "Association tests and mouse experiments have indicated that CNTN4 is an obesity–insulin targeted gene." (PMID 25898945, 2015).
alcohol use disorder (1 paper, 2025). "CNTN4 has been described as a risk factor for alcohol use56, and increased alcohol use disorder has been widely reported after GBS57." (PMID 39753963, 2025).
atherosclerosis (1 paper, 2022). A disease characterized by the build-up of fatty material and calcium deposition in the arterial wall resulting in partial or complete occlusion of the arterial lumen. "The CNTN4 genotypes were indicated to be correlated with an excess of cardiovascular events, but how CNTN4 influenced atherosclerosis was not clarified in our study." (PMID 35915606, 2022). "In GSE20129 dataset, CARTPT, RYR2, CNTN4, PDZRN3, and SLC22A3 all showed differential expression levels in atherosclerosis vs. nonatherosclerotic samples." (PMID 35915606, 2022).
chronic kidney disease (1 paper, 2021). Impairment of the renal function secondary to chronic kidney damage persisting for three or more months. "The CNTN4 gene has been implicated with MetS traits and serum uric acid levels, and positively associated with increased risk for chronic kidney disease and cardiovascular disease." (PMID 34074324, 2021).
emotional dysregulation (1 paper, 2021). "Another notable observation is that ADHD patients with a CNTN4 mutation phenotype tend to be more severe, with a higher prevalence of emotional dysregulation and demonstrate enriched response to fasoracetam." (PMID 33671795, 2021).
metabolic syndrome (1 paper, 2022). A cluster of metabolic risk factors for CARDIOVASCULAR DISEASES and TYPE 2 DIABETES MELLITUS. "In the metabolic syndrome sub-network, five genes had high degrees of connection and could be considered hub genes: PTPRD, DCC Netrin 1 Receptor (DCC), Proprotein Convertase Subtilisin/kexin Type 6 (PCSK6), Unc-13 Homolog C (UNC13C), and Contactin 4 (CNTN4)." (PMID 35121771, 2022).